CD40 (CD40 molecule)
Diseases named in the same sentence as CD40 in open-access papers (continued):
Sharing a sentence is not in itself a finding about the gene and the disease.
glioma (44 papers, 2018 to 2025). A benign or malignant brain and spinal cord tumor that arises from glial cells (astrocytes, oligodendrocytes, ependymal cells). "Increased CD40/CD40L expression in gliomas is associated with good prognoses and CD40 agonism enhances intratumoral T-cell responses in glioma patients." (PMID 35456932, 2022). "TLS have been found in both patient gliomas and in glioma-bearing mice where their formation was found to be enhanced by injection of agonistic α-CD40 antibody." (PMID 41066027, 2025). "In an adult glioma preclinical model, using a CD40 mAb enhances the anti-tumor efficacy of tumor lysate-based vaccines." (PMID 40578365, 2025). "Agonistic CD40 therapies, notably αCD40-induced tertiary lymphoid structures, are instrumental in shaping the immune landscape within gliomas." (PMID 38342925, 2024). "LAPTM5 knockdown resulted in CD40-mediated NF-B activation, which enhanced invasion, clonality, and temozolomide resistance in glioma." (PMID 39281638, 2024). "Recent studies have demonstrated that the immunostimulatory agonistic CD40 antibody (αCD40) induces the formation of TLS near meningeal tissues in preclinical glioma models." (PMID 39175478, 2024). "Specifically, LAPTM5 exhibits tumor suppression and sensitivity to temozolomide by inhibiting the CD40-mediated NF-kB activation in CD40-positive gliomas." (PMID 39281638, 2024). "The immunohistochemical results showed that PD-1, PD-L1 and CD40 expression increased with the increasing TANK expression in glioma." (PMID 37215097, 2023). "In the context of glioma, the administration of agonistic antibodies against CD40 was tested in preclinical models." (PMID 35267626, 2022). "ALKBH5 expression showed positive association with ICP receptors such as TNFRSF14, CD40, CD96 and CD200R1, and ICP ligands such as PDCD1LG2, CD70, TNFSF14, ICOSLG and CD274 in glioma tissues." (PMID 35444654, 2022). "Preclinical work in glioma has suggested that agonistic CD40 impairs response to PD-1 blockade in part through the induction of regulatory B cells." (PMID 35662283, 2022). "Immunostimulatory agonistic CD40 antibodies (αCD40) are in clinical development for solid tumors, but are yet to be evaluated for glioma." (PMID 34226552, 2021). "In glioma cells, ligation of CD40 can induce upregulation of vascular endothelial growth factor (VEGF) and shows a correlation with tumor size." (PMID 34771550, 2021). "We finally analyzed The Cancer Genome Atlas (TCGA) data sets to investigate the role of IL-6 and CD40 in human patients with GBM or glioma." (PMID 34103524, 2021). "In a glioma model, release of soluble CD40 from platelets has been reported; this is a known inhibitor of regulatory T cell recruitment, which promotes an immunosuppressive microenvironment and ultimately a pro-tumor milieu." (PMID 34178693, 2021). "As CD40 is known to be involved in several immune effects, we excluded that the observed association of CD40 high-expressing and LAPTM5 high-expressing gliomas with better prognosis is related to differences in the signature of immune cells." (PMID 32582531, 2020). "Beyond these immune-modulating effects, CD40 signaling was shown to be involved in apoptosis and the neovascularization of glioma cells." (PMID 32582531, 2020). "It has been shown that most high-grade gliomas express CD40 with an observed high CD40 expression in about 40% of the tumor samples in patient-derived tumor tissue." (PMID 32582531, 2020). "Previous studies demonstrated contradicting results about the correlation of CD40 expression with the survival of glioma patients." (PMID 32582531, 2020). "Based on patient survival data and functional in vitro and in vivo experiments, we concluded that LAPTM5 acts as a tumor suppressor in CD40-positive gliomas." (PMID 32582531, 2020). "In a mouse glioma model, it has been found that DCs downregulate costimulatory molecules (CD40, B7.1, B7.2) and are unable to stimulate T cells." (PMID 31234870, 2019).
glioma (continued). "However, high CD40 expression was detected in glioma biopsy samples and correlated with lesions and an increased vascularization." (PMID 40895574, 2025). "CD40 was upregulated in secondary gliomas as contrasted with primary gliomas." (PMID 40895574, 2025). "Indeed, others showed higher expression of CD40 by grade 3 Gliomas than GBM and slower progressing GBMs." (PMID 35207340, 2022). "Furthermore, the beneficial effect of CD40 ligation in combination therapy has been established in mouse models of glioma, in which CD40 ligation improved the efficacy of therapeutic approaches including COX-2 inhibition and several cancer vaccines." (PMID 34771550, 2021). "Agonistic CD40 antibodies (αCD40) have broad immunostimulatory properties, however their efficacy in glioma remains unclear." (PMID 34226552, 2021). "LAPTM5 and CD40 were correlated with the clinical outcome of glioma patients." (PMID 32582531, 2020). "Interestingly, WHO grade III gliomas express higher CD40 and CD40L levels compared to GBMs." (PMID 40895574, 2025). "Thus, targeting CD40 in GBM has been proposed, partly to stimulate immune responses, partly based on reported slightly faster progression among higher CD40 expressing gliomas, including GBMs, although levels of CD40 are generally low in GBM compared to some other cancers and among GBM cell lines." (PMID 35207340, 2022). "In addition, LAPTM5 inhibits tumor invasion, clonogenicity, and tumorigenicity by inhibiting NF-κB activation, which may act as a therapeutic target for CD40+gliomas." (PMID 36385959, 2022). "However, TLS formation induced by immunostimulatory agonistic CD40 antibodies was observed to impair the efficacy of anti-PD-1 antibodies (αPD-1) in murine gliomas through the accumulation of CD11b-expressing B cells, which may inhibit CD8+ T cell responses." (PMID 34954691, 2021). "Here CD40 induction might lead to a further activation of the NFκB pathway and thereby to resistance toward temozolomide treatment and fostering the aggressiveness of gliomas." (PMID 32582531, 2020). "In glioma, one study reported the formation of TLS structures in mice following agonistic CD40 therapy." (PMID 39880824, 2025). "The results of our investigation showed a strong relationship between the expression of SMARCAL1 and several immune checkpoint genes, including CD276, NRP1, TNFSF4, CD40, CD200, and CD80 in Glioma, LUAD, LIHC, KIRC, and UCEC." (PMID 39994264, 2025). "The interplay between CD40 and the glioma microenvironment reveals a nuanced and multifaceted role of this TNF receptor family member in glioma biology." (PMID 38342925, 2024). "The CD40/CD40L axis is under investigation for its role in the progression and treatment of both primary and secondary brain tumors including gliomas." (PMID 35456932, 2022). "Clinically, high expression of CD40L, clusters of differentiation 40 (CD40) and LOX correlated with poor survival in patients with glioma." (PMID 35908277, 2022). "The in silico analysis revealed that CD40 high-expressing and LAPMT5 high-expressing gliomas had a better prognosis, which was attributed to the tumor tissue and not to the immune cells." (PMID 32582531, 2020). "In our study, we found that CTLA-4 was significantly correlated with PD-1, CD40, and ICOS in patients with glioma and glioblastoma." (PMID 31911758, 2020). "However, the survival outcome in the SB28 glioma-bearing mice is worse than GL26 tumors and several factors could play a role, including the weak immunogenicity of SB28 tumors and deficiency of the expressing xenogeneic epitopes, such as CD40." (PMID 30333031, 2018). "Interestingly, CD40, and also CD40L to some extent, were found to be expressed by human gliomas and the CD40/40L co-expression in glioma patients serves as a positive prognostic factor." (PMID 35267626, 2022). "Even though CD40 antagonistic antibody treatment shows auspicious results in glioma preclinical models, it has not yet been tested in clinical trials for GBM treatment." (PMID 35267626, 2022).
glioma (continued). "In fact, glioma-infiltrating microglia do not seem to express co-stimulatory molecules, including CD40 or much cytokine expression potential, such as IL-6 in the absence of inflammatory stimuli." (PMID 35207340, 2022). "To investigate the effects of agonistic CD40 antibodies (αCD40) on the tumor microenvironment, we intravenously administered αCD40 or the corresponding rIgG2a isotype control to C57BL/6 mice with syngeneic gliomas." (PMID 34226552, 2021). "Gliomas with a high TME-score expressed more immune checkpoints, such as LAG3, CD40, and PDCD1LG2." (PMID 34489938, 2021). "In contrast, expression of IL-4, another important cytokine that regulates Mφ and T-cell functions similar to IL-6, did not correlate with CD40 expression in patients with GBM or all grades of glioma." (PMID 34103524, 2021). "It has been reported that CD40, TNFSF14, LGALS9, and SIGLEC10 high expression levels are associated with glioma malignancy grade and negative prognosis." (PMID 35187044, 2021). "SB28-GFP is a newly developed mouse cell line, which does not express detectable CD40, and represents a weakly immunogenic glioma model." (PMID 30262908, 2018). "Several preclinical studies have demonstrated the value of anti-CD40 agonist treatment in reprogramming GAMs and boosting anti-tumor immunity, e.g. in combination with CSF-1R blockade, IL-6 inhibition or with the microtubule-disrupting agent lisavanbulin (BAL101553) in treating ICI-resistant glioma." (PMID 40642066, 2025). "However, other studies measuring expression of CD40 in grades II, III, and IV gliomas established a negative correlation between CD40 expression and patient survival." (PMID 35456932, 2022). "Therefore, we hypothesized that high ALKBH5 expression altered the immune microenvironment in the glioma tissues by modulating the expression levels of ICP receptors and ligands such as TNFRSF14, CD40, CD96, PDCD1LG2, CD70 and TNFSF14." (PMID 35444654, 2022). "Glioma-associated macrophages and microglia produce low levels of pro-inflammatory cytokines and lack expression of key molecules involved in T-cell co-stimulation, such as CD86, CD80, and CD40, indicating that they may be negative inducers of T-cell response in glioma." (PMID 37543576, 2023). "Glioma-infiltrating microglia/macrophages from postoperative tissue samples of glioma patients expressed surface MHC-II but lacked the expression of the co-stimulatory molecules CD86, CD80, and CD40, which are critical for T cell activation." (PMID 40281508, 2025).
COVID-19 (42 papers, 2020 to 2025). A disease caused by infection with severe acute respiratory syndrome coronavirus 2. "Upon reviewing the literature, we postulate that tumor necrosis factor (TNF) and its receptors, CD40L/CD40, along with the cell surface receptor sTREM-2, are implicated in COVID-19-induced CSVD." (PMID 40491910, 2025). "The results of the leave-one-out method showed that the causal relationship between CD40 and severe COVID-19 was robust, while FAS required caution." (PMID 37397483, 2023). "Our genetic evidence suggests that FAS is positively associated with the severity of COVID-19 and that CD40 is protective against severe COVID-19." (PMID 37397483, 2023). "In this regard, studies of CD40 rs4813003 polymorphism are important in relation to COVID-19 and MIS-C because cardiovascular system involvement is typical for both of them, especially MIS-C." (PMID 37896870, 2023). "GSVA analysis with COVID-19 vaccine RNA-seq data as the reference identified 1854 immune infiltration gene sets, with 200 associated with vaccination and 72 significant, including CD40 and CXCR4." (PMID 41232126, 2025). "Allele T ACE2 rs2074192 (OR = 3.45; p = 0.009), allele A IFNAR2 rs2236757 (OR = 2.62; p = 0.039), allele A OAS1 rs10774671 (OR = 4.60; p = 0.003) and allele C CD40 rs4813003 (OR = 4.75; p = 0.037) are associated with severe COVID-19 that could advance to MIS-C." (PMID 37896870, 2023). "Platelet-derived sCD40L promotes CD40-positive cell activation and thrombogenesis by stabilizing integrin αIIbβ3 in COVID-19." (PMID 40491910, 2025). "Analysis of platelet characteristics in COVID-19 revealed that these platelets have increased reactivity (increased aggregation and expression of P-selectin and CD40) and unique transcriptional characteristics of prethrombotic large and immature platelets." (PMID 38348024, 2024). "Regression analysis showed that COVID-19 susceptibility in children increases in cases of interactions of IFNAR2 rs2236757, OAS1 rs10774671, OAS3 rs10735079, CD40 rs4813003 and CASP3 rs113420705." (PMID 37896870, 2023). "Genetically predicted CD40 levels were significantly negatively correlated with severe COVID-19 (IVW, OR = 0.92, 95% confidence interval (CI) = 0.87–0.97, p = 0.002)." (PMID 37397483, 2023). "The study revealed that ACE2 rs2074192 (allele T), IFNAR2 rs2236757 (allele A), OAS1 rs10774671 (allele A), CD40 rs4813003 (allele C), CASP3 rs113420705 (allele C) and male sex contribute to severe COVID-19 course and MIS-C in 85.6% of cases." (PMID 37896870, 2023). "The multifactorial analysis shows that, in addition to ACE2, IFNAR2, OAS1, and CD40 genes, the CASP3 rs113420705 gene (allele C) makes the clinical outcome of COVID-19 in males worse." (PMID 37896870, 2023). "Such indicators as male sex, ACE2 rs2074192 allele T, IFNAR2 rs2236757 allele A, OAS1 rs10774671 allele A, CD40 rs4813003 allele C and CASP3 rs113420705 allele C can predict severe COVID-19 course and MIS-C in the pediatric population in 85.6% of cases." (PMID 37896870, 2023). "Sensitivity analysis did not reveal heterogeneity (MR‒Egger, Q_P-val = 0.483; IVW, Q_P-val = 0.497) or significant horizontal pleiotropy (intercept = 0.005, se = 0.006, p = 0.388) for CD40 with severe COVID-19." (PMID 37397483, 2023). "Two other naïve phenotypes were apparent, differing by their expression of CD40, of which the CD40-ve population appeared to be unique to the HIV-ve COVID-19+ participants (red population)." (PMID 36300787, 2022). "Compared to mild cases, severe COVID-19 showed upregulated CD40 together with downregulated CD83, HLA-DQA2 and FCER1A in all three tissues." (PMID 34502134, 2021). "Next, we compared expression of markers associated with cell activation (CD40), maturation (CD16), homing (CXCR6), tissue recruitment (CD62L), and polarization (CD163) on monocytes and DC subsets in young and aged COVID-19 patients relative to healthy donors." (PMID 34707619, 2021).
COVID-19 (continued). "Two cytokine-associated genes (CCL4 and CD40) were dysregulated in COVID-19 and single VTE, and one cytokine-associated gene (CCL4) was dysregulated in COVID-19 and recurrent VTE." (PMID 34071557, 2021). "We found severe COVID-19 patients had significantly more CD40+CD16Int LDNs than moderate patients as assessed by flow cytometry." (PMID 33986193, 2021). "HLA-DR and CD40 expression were significantly lower in B cells of severe COVID-19 patients compared to B cells in healthy donors." (PMID 33692788, 2021). "The role of CD40 in COVID-19 is mainly applicable to vaccines." (PMID 37397483, 2023). "Therefore, CD40, FCGR2A and CASP3 genes are discussed as the genetic predisposition factors of KD, as well as severe COVID-19 and MIS-C, in children." (PMID 37896870, 2023). "In conclusion, this MR study provides genetic evidence supporting that increased expression of FAS may be associated with the risk of severe COVID-19, with a possible protective effect of CD40 against COVID-19." (PMID 37397483, 2023). "Therefore, based on the model, the key components of COVID-19 susceptibility in childhood are alleles of genes IFNAR2 rs2236757, OAS1 rs10774671, OAS3 rs10735079, CD40 rs4813003 and CASP3 rs113420705." (PMID 37896870, 2023). "Gene expression from COVID-19 patients was enriched for signatures of granulocytes, including inflammatory neutrophils and low-density granulocytes (LDGs) as well as plasma cells (PCs) and CD40 activated B cells." (PMID 36189236, 2022). "Additionally, CD40 expression was higher in these aggregates, and the frequency of CD40+CD16Int LDNs highly correlated with D-dimer levels in patients with COVID-19." (PMID 33986193, 2021). "Moreover, increased CD40 expression by CD16Int LDNs significantly correlated with increased D-dimer levels in severe COVID-19 patients." (PMID 33986193, 2021). "Previously, we have published and demonstrated the specific roles of the ACE2 rs2074192, IFNAR2 rs2236757, OAS1 rs10774671, CD40 rs4813003, and CASP3 rs113420705 genes in predicting severe COVID-19 and multisystem inflammatory syndrome (MIS-C) in children." (PMID 40066463, 2025). "Additionally, by examining genes associated with Kawasaki disease (CD40, FCGR2A, CASP3), our study highlights potential common pathways in hyperinflammatory responses, suggesting that insights gained from COVID-19 could be applicable to other pediatric inflammatory conditions." (PMID 40066463, 2025). "Future studies should measure both CD40 and CD40L to fully elucidate their roles in immune modulation and severe COVID-19 outcomes." (PMID 39654974, 2024). "In the COVID-19 group, the TYK2 rs2304256, OAS1 rs10774671, CD40 rs4813003 and FCGR2A rs1801274 homozygote and heterozygote frequencies were in accordance with those indicated by the Hardy–Weinberg principle (p > 0.05)." (PMID 37896870, 2023). "Crucial factors for the development of severe COVID-19 or MIS-C are sex (male gender), ACE2 rs2074192, IFNAR2 rs2236757, OAS1 rs10774671, CD40 rs4813003 and CASP3 rs113420705." (PMID 37896870, 2023). "Therefore, our result, conforming with previous reports, indicates that simultaneous upregulation of CD40, Flt3L, IL-6, IL-8, and LIF, in association with CAPG and EDIL3, plays a pivotal role in inflammation and recruitment of immune cells in lung tissues of COVID-19 patients." (PMID 36428847, 2022). "In this study, we found several exosomes including CD9, CD31, CD40, CD45, CD41b, CD42a, CD62P, CD69, CD81, CD105, and HLA-DRDPDQ in the plasma of COVID-19-recovered pregnant women were significantly less abundant than the control group." (PMID 35647028, 2022). "The gradual decrease in the expression of CD40 and CD40LG in the COVID-19 positive and recovered groups suggest an enhanced infection-induced inflammation and apoptosis of CD8+ T cells during COVID-19 infection." (PMID 36532041, 2022).